CCND1 (cyclin D1)
Diseases named in the same sentence as CCND1 in open-access papers (continued):
Sharing a sentence is not in itself a finding about the gene and the disease.
tumor (continued). "Ournovel approach of combining two tumor markers (p63 and cyclin D1) to predict LVI and PNI ascritical indicators of disease progression in OSCC has shown promising results and willprompt further research into this field." (PMID 36716784, 2023). "On the other hand, CTNNB1 knockdown inhibits the Wnt/β-catenin signaling pathway and downregulates the expression of downstream genes, including axin 2, lymphoid enhancer-binding factor 1 (LEF1), and cyclin D1, thereby inhibiting tumor proliferation." (PMID 37033970, 2023). "The most widely‐mutated genes across all tumor types include CDKN2A and RB1, most frequently loss‐of‐function, and CCND1, which usually increases in copy number." (PMID 37718413, 2023). "This treatment also resulted in reduced tumor size, decreased expression of Cyclin D1, a lower Ki67 proliferation index, and improved animal survival, compared to the non-treated group." (PMID 37686276, 2023). "The TNM plots revealed a high expression of c-Met/GSK3β/MYC/CCND1 in tumor tissues compared to normal colon tissues." (PMID 36672275, 2023). "Our study found that ferulic acid significantly reduced the activation of both cMyc and cyclin D1, leading to antitumor activity and a decrease in tumor weight and size." (PMID 37465088, 2023). "For example, in the first mode, a driver-upregulating mutation in the regulatory region of CCND1 (Cyclin D1) is predicted to break binding of HIC1, a transcriptional repressor TF and a candidate tumour suppressor gene." (PMID 36625266, 2023). "CCND1 expression correlates directly with tumor grade, increases proliferation, and contributes to temozolomide resistance." (PMID 37370851, 2023). "We identified amplifications in oncogenes, including FCGR2B and CCND1, and deletions of tumor suppressors, such as CCNC and RB1, only in HPV-negative tumors." (PMID 37461056, 2023). "Cyclin D1 is an important regulatory target of the G1-S phase transition and is closely related to tumor cell proliferation." (PMID 37626050, 2023). "They form a complex with cyclin D1 to jointly regulate tumor proliferation, and this complex is becoming a new target for tumor therapy." (PMID 36776322, 2023). "Cyclin D1 is a cell cycle regulatory protein, and its abnormal isoforms can participate in important processes such as tumor cell cycle, invasion, and metastasis." (PMID 38102686, 2023). "Wnt signaling pathway (canonical or non-canonical) helps in the proliferation and evade apoptosis of tumor cells via regulation of survivin, c-Myc, and cyclin D1." (PMID 36715825, 2023). "AIB1 supports tumor cell proliferation in part through enhancing ERα-dependent gene transcription, such as cyclin D1 and the PR." (PMID 37711895, 2023). "In this context, it is notable that amplification of the gene encoding the CDK2 partner cyclin E1, is even more common than CCND1 amplification across numerous human tumor types." (PMID 37718413, 2023). "Elevated expression of cyclin D1 was also found in tumor tissues compared to normal counterparts in a cohort of ESCC patients." (PMID 37041169, 2023). "ERK signaling promotes tumor cell proliferation, invasion, and migration by elevating cyclin D1 and matrix metalloproteinases (MMPs)." (PMID 37626050, 2023). "Several tumor characteristics such as nuclear grade, estrogen receptor alpha, progesterone receptor, triple-negative phenotype, Cyclin D1 immunohistochemistry, and Mucin 1 differed significantly between the created groups." (PMID 36769215, 2023).
tumor (continued). "Incorporating these EVs by bystander tumor cells resulted in decreased proliferation and viability, accompanied by a reduction in CCND1 and YAP1 mRNA levels." (PMID 37174717, 2023). "As we measured β-catenin levels in isolated cells, we found higher activation of β-catenin and induction of Wnt target genes, including Ctnnb1, cMyc, and Ccnd1, in Nlrp12–/– tumor epithelial cells." (PMID 37581937, 2023). "This approach led tumor cells to apoptosis and suppressed mRNA and protein expression levels of β-catenin, c-myc, and cyclin D1, respectively." (PMID 37046740, 2023). "Several authors have reported that PGG treatment downregulated cyclin D1 in several cancer cell lines, thereby leading to tumor suppression." (PMID 37375411, 2023). "MiR-9 can suppress the proliferation of malignant tumor cells by downregulating CDK6 and cyclin D1, causing cell cycle arrest in the G0/G1 phase." (PMID 37240281, 2023). "The downregulation of cyclin D1 and the anti‐apoptotic Bcl2 is in line with a reduction of the rate of tumour cell proliferation and induction of apoptosis, respectively." (PMID 37390227, 2023). "Further evidence of aggressive tumor growth of the WSHFD-EL4 mice was showed by Western blot analysis of the protein levels of cyclin D1, c-Myc, and E-cadherin and Vimentin for epithelial–mesenchymal transition (EMT) in comparison with the CD-EL4 mice." (PMID 36600310, 2023). "Out of these 5 hub genes, only CCND1 have high median mRNA expression in normal patients than primary tumor whereas AXL, CDKN2A, TERT, and EZH2 have high expression in the primary tumor." (PMID 36715825, 2023). "matrine increased the sensitivity of lung CSCs to 5-FU and inhibited the accumulation of CCND1 in tumor tissues induced by 5-FU." (PMID 37841927, 2023). "Although Cyclin D1 is well recognized for its function in the nucleus, current clinical investigations link it to tumor invasion and metastasis when it is present in the cytoplasmic membrane." (PMID 37081847, 2023). "Further, the prognostic impact of cyclin D1 expression was investigated with respect to tumor stage." (PMID 37894399, 2023). "GSK3B is an effector downstream of ErbB signaling that plays an important role in tumor proliferation by directly regulating P21 and Cyclin D1." (PMID 38017514, 2023). "It was revealed that, CCND1, which was reported to be a modulator in tumor progression via promoting cell cycle progression, was among the candidates." (PMID 36760720, 2023). "In the future, with sufficient time and funding, we will continue to explore how Ambra1 affects cyclin D1 expression, migration, invasion, and apoptosis in tumor cells through autophagy and the molecular mechanism by which Ambra1 regulates cyclin D1." (PMID 37225761, 2023). "Further studies are thus needed to understand the pivotal role of cyclin D1 in shaping the development of the tumor microenvironment and in its therapeutic efficacy for successful clinical translation to treating patients with cancer." (PMID 36675501, 2023). "This was consistent with our finding that CCND1 is highly expressed in tumor cells (Plasma-2) in P2 by the scRNA-seq method." (PMID 38035111, 2023). "Pearson’s x2 test was performed to assess associations between PAK1 CN and tumour features, and between PAK1 and CCND1 CNs." (PMID 37368917, 2023). "Marked hyperactivation of PI3K signalling was observed in the tumours along with expression of the cell proliferation markers Ccnd1 and pMet, the epithelial marker Cdh1 and the phosphorylation of Ybx1, but not the p-EMT marker Pdpn." (PMID 36949044, 2023). "Accordingly, Ccnd1 is classified as an oncogene frequently amplified in many types of neoplasia, and different cancer treatments with Cdk4/6 inhibitors such as Palbociclib have been approved to block this function." (PMID 37684532, 2023). "The oncogenic activity of CCND1 is strongly tied to its cellular levels, as tumour cells with high CCND1 levels exhibit uncontrolled cell proliferation." (PMID 37510349, 2023).
tumor (continued). "In the same study, it was seen that HBV_circ_1 induces cell proliferation and migration, blocks apoptosis in vitro, promotes Ki67 and cyclin D1 expression in the formed tumour tissue and increases tumour size in vivo." (PMID 38003737, 2023). "Elevated levels of cyclin D1 have been detected in various tumor types, including hepatocellular, head and neck, esophageal, lung cancers, and OSCC." (PMID 38067304, 2023). "Our data also show that, in Suit-2 cells, cyclin D1 levels are unaffected by K-Ras depletion, therefore the transcriptional activation of cyclin D1 by K-Ras is probably of little importance in an established tumour." (PMID 36975534, 2023). "Activation of these cells produces pro-thrombotic and pro-tumorigenic TF and activates STAT3-mediated IL-6, PAI-1, and MMP-2 production (black upward arrows), and RAS/PI3K/SyK/Ki67/cyclin D1 signaling pathways, leading to tumor growth." (PMID 36751299, 2023). "Treatment with ORIC-101 reduced tumor levels of phospho-EGFR and cyclin D1 and suppressed tumor growth in a dose-dependent manner, with 150 mg/kg resulting in a median growth inhibition of 50%." (PMID 37691854, 2023). "Cyclin D1 is known to drive cell cycle progression, while c-Myc regulates cyclin D1 to induce proliferation and tumor growth." (PMID 36982817, 2023). "Consistently, the expression of cell proliferation marker CCND1 was decreased in Apc/Drp1-KO tumor organoids as determined by RT-qPCR analysis." (PMID 37816729, 2023). "In this context, it is worth mentioning that the overexpression of both cyclin D1 and E1 can be considered as a marker of oncogenesis for several tumor types, including OC." (PMID 36834730, 2023). "PLAGL2 combines with the Wnt6 promoter and activates the β-catenin-dependent Wnt signaling pathway, thereby stimulating various downstream target genes (such as MMP7, CCND1) and promoting tumor development." (PMID 38003292, 2023). "Cyclin D1 functions as a cell cycle regulator; and its overexpression promotes tumor growth by allowing unregulated cellular proliferation." (PMID 36882428, 2023). "A high cyclin D1 H score was also strongly related to a well-differentiated grade and an early tumour stage (p = 0.016 and p = 0.042, respectively VEGF H score was significantly higher in well-differentiated grade (p = 0.040)." (PMID 38414954, 2023). "p38 functions as a tumor repressor, since p38 activation leads to apoptosis, senescence, and differentiation, and p38 inhibits the expression of Cyclin D1 activated by RAS to suppress S phase transition." (PMID 38041111, 2023). "In summary, we have shown that MG53 is a tumor suppressor that targets cyclin D1 for ubiquitination-dependent degradation." (PMID 37414783, 2023). "By targeting the Wnt/CCND1 pathway to prevent 5-fluorouracil-induced CCND1 accumulation in tumor tissues, matrine sensitized NSCLC cells to the effects of 5-fluorouracil in vivo and markedly boosted apoptosis." (PMID 37841927, 2023). "Cyclin D1 is a major driver of multiple cancers including MM, through overexpression in either the cytoplasm or nucleus where it promotes tumor invasion/metastasis or deregulation of cell cycle control/enhanced proliferation, respectively." (PMID 37301510, 2023). "In the present study, we assess the expression of cyclin D1 in both normal colonic mucosa and tumor cells of CRCs, in addition to the clinicopathological and prognostic significance of cyclin D1 expression in CRCs." (PMID 36675501, 2023). "First, ssCHK1 and ssBRD4 hindered G1/S transition cell cycle progression by depleting MYC and cyclin D1 levels, while simultaneously upregulating tumor suppressor genes in HCC, preventing cell growth in target cells." (PMID 36684069, 2023).
tumor (continued). "Cyclin D1 was observed in 40% of cases in adjacent non-tumour liver, while EGFR and VEGF were detected in 88.9% and 61.1%, respectively." (PMID 38414954, 2023). "We compared the expression level of six frequently used markers for WNT activation (CTNNB1/beta-catenin, TCF1, TCF4, FZD7, MYC and CCND1) in normal and tumor tissue." (PMID 37149691, 2023). "Wang and Liu found a statistically significant correlation between cyclin D1 expression and tumor thickness and depth of invasion (DOI)." (PMID 36982894, 2023). "Cyclin D1 analysis in untreated tumor tissue exhibited provoked expression of Cyclin D1 in contrast to normal control; however, this elevation in gene expression was reduced as a result of CuNPs and/or gamma radiation treatments." (PMID 36905557, 2023). "Peptidyl-prolyl cis-trans isomerase NIMA-interacting 1 (PIN1) contributes to the upregulation of cyclin D1, either directly or via the abnormal accumulation of β-catenin in tumor cells." (PMID 37427143, 2023). "These exosomes increase the expression level of cyclin D1 and accelerate tumor cell proliferation by inducing the transfer of KIT protein that binds to the SCF in the tumor cells and leads to the PI3K/AKT signaling pathway." (PMID 35550636, 2022). "In fact, knockdown of DDX3X upregulates cyclin D1 and downregulates p21, thus promoting cell cycle progression to the S phase and facilitating tumor cell growth." (PMID 35954483, 2022). "Expression levels of c-Myc, Ccnd1, and Vim were lower in Tubb4a/Pten-cKO versus Pten-cKO tumor cells, supporting indirect transcription regulation of these β-catenin targeted genes by TUBB4A." (PMID 35589707, 2022). "There was good concordance between CCND1 CN increase in the primary tumours and in the corresponding lymph node metastases." (PMID 35459982, 2022). "At molecular level, circFAT1 sequestered miR-7 to upregulate IRS2, which in turn regulated downstream ERK1/2 phosphorylation and CCND1 expression, ultimately promoting tumor progression." (PMID 35844799, 2022). "In the same time, Cyclin D1 expression was downregulated in tumor cells of Thymax post-treated and pretreated groups (p < 0.01) by 45.7% and 75.7%, respectively, versus Inocul Control mice." (PMID 35299600, 2022). "In the context of the clinical trial, the authors were unable to confirm the in vivo delivery of the miRNAs to the tumor site or to detect changes in Bcl-2 and CCND1 expression." (PMID 35205318, 2022). "The administration of GYY4137 for 24 h inhibits the cyclin D1, inhibiting the transition of the G1/S cell cycle and tumor growth in the Xenograft model of the subcutaneous HepG2." (PMID 35684331, 2022). "HIF1-α, VEGF, Cyclin D1, Wnt1, and β-catenin expression in the tumor was detected by Western blotting." (PMID 35711625, 2022). "Regorafenib suppresses cell proliferation and tumor growth in HCC by decreasing cyclin D1 via alterations in intracellular and exosomal miRNAs in HCC." (PMID 35163589, 2022). "PHGDH reportedly modulates FoxM1 expression, thus promoting the expression of the cell proliferation marker gene cyclin D1 and the proliferation of tumor cells." (PMID 35344765, 2022). "These analyses revealed that WTS and qRT-PCR expression values correlate significantly across MCL tumor samples and reactive tonsil B-cell subset samples for both CCND1 and SNHG5." (PMID 36359790, 2022).
tumor (continued). "In a mouse model of CAC, Ya-Chun Chou demonstrated that Boswellia serrata mediated Akt/GSK3β/cyclin D1 signaling pathway and altered the composition of gut microbiota to alleviate tumor growth." (PMID 35733095, 2022). "In contrast, the cyclin D1, CDK4 and pRB proteins are present at reduced levels that explain the observed cell cycle arrest in IFITM3-deficient tumor cells." (PMID 36466909, 2022). "LKB1 is now recognised as a tumour suppressor that acts through the mTOR pathway by inhibiting the activation of important proliferative oncogenes such as CCND1/CD1 and Myc." (PMID 35954497, 2022). "Since expressions of c-MYC, cyclin D1, and vimentin were reduced after TUBB4A KO, we analyzed the mRNA expression of β-catenin-targeted genes c-Myc, Ccnd1, and Vim in microdissected tumor cells." (PMID 35589707, 2022). "RelA is the regulatory subunit of NF-κB in nucleus, essential for the transcriptional activity of NF-κB, which is crucial for cyclin D1 expression, tumor formation and metastasis." (PMID 36743909, 2022). "We verified the effect of CCND1 inhibition by NF-κB inhibitor SN50 in tumor tissues with changes in the pathway activity of PI3K/AKT." (PMID 35246017, 2022). "An increasing number of studies have shown that cyclin D1 plays an important role in tumour proliferation." (PMID 36396671, 2022). "These regions contained tumor-related genes, such as Muc16, Pik3, and Bcl2 in amplification regions and Hras, Notch1, Apc2, Ccnd1, Batf2, Dapk3, Smarca4, Traf2, Traf3, Cdk3, and Cdh4 in deletion regions." (PMID 36424557, 2022). "TAPC‐4 can downregulate cyclin D1 expression and subsequently RB phosphorylation to block the cell cycle in G0/G1 phase, resulting in the inhibition of tumor cell proliferation with IC50 values of approximately 10 μm." (PMID 36031401, 2022). "In three of four tumor specimens, an increase in Rb protein and a decrease in cyclin D1 were noted by immunohistochemical analysis." (PMID 35215257, 2022). "Previously, cyclin D1 was reported to be abnormal in a variety of cancers and is closely related to the abnormal proliferation of tumor cells." (PMID 33656636, 2022). "The expression of MMP9 and cyclin D1 was also suppressed in anti‐Chi3L1 antibody‐treated lung metastasis tumor tissues." (PMID 34861103, 2022). "Cyclin D1 and Cyclin E1 are two crucial G1/S transition regulatory factors that are often deregulated and play oncogenic roles in tumor proliferation and progression." (PMID 34975298, 2022). "There was good correlation between primary tumours and axillary lymph node metastases with regard to CCND1 CN." (PMID 35459982, 2022). "It has been shown that tumours coamplified for FGFR1 and CCND1 are associated with an especially poor prognosis." (PMID 35459982, 2022). "Studies have discovered that cyclin D1 level is closely correlated with tumor stage, degree of differentiation and lymphatic metastasis, and it is considered to be an important indicator for evaluation of tumor malignancy." (PMID 35929837, 2022). "In contrast, the overexpression of NDUFA4 significantly promoted tumor growth and expression of Cyclin D1 and CDK4 in tumor xenograft." (PMID 35977935, 2022). "Collectively, our data provide a strong rationale for clinical testing of dual targeting of FGFR and CCND1/CDK4 in NSCLC patients with FGF3/4/19/CCND1-amplification tumor resistant to gefitinib." (PMID 35814257, 2022). "Nuclear SIRT1 will bind to the LEF1 lysine residue to deacetylate the present histones regulating the transcription of the downstream targets such as cyclin D1, C-Myc, and surviving, thereby inducing tumour proliferation and migration." (PMID 36505828, 2022). "Immunohistochemistry also showed lower expression levels of stemness markers, Notch-related, and Wnt-related genes, including HES1 and CYCLIN D1, in the SHMT2-deficient tumor groups than in the control tumor group." (PMID 36077112, 2022).